RN7SKP277 (RN7SK pseudogene 277)
Gene: Miscellaneous RNA gene on chromosome 7 (121,736,443 to 121,736,725, forward strand). Ensembl gene ENSG00000252704.
Homologues: Orthologues: chimpanzee 7SK (100% identical). Paralogues in human: RN7SKP134 (57% identical), RN7SKP118 (56% identical), RN7SKP37 (56% identical), 7SK (55% identical), RN7SKP130 (55% identical), RN7SKP124 (55% identical), RN7SKP250 (55% identical), RN7SKP78 (55% identical), RN7SKP15 (55% identical), RN7SKP191 (55% identical), RN7SKP192 (55% identical), RN7SKP217 (55% identical), and 283 more.